FGF8 (fibroblast growth factor 8)
Diseases named in the same sentence as FGF8 in open-access papers (continued):
Sharing a sentence is not in itself a finding about the gene and the disease.
ovarian carcinoma (5 papers, 2014 to 2024). A malignant neoplasm originating from the surface ovarian epithelium. "Hub genes identified in the FGF8 protein network were upregulated in ovarian cancer compared to controls and were linked to poor prognosis." (PMID 39309198, 2024). "Further, gene enrichment and pathway analysis revealed that several GO terms and KEGG pathways that are known to aid in cancer progression were associated with downregulated proteins in FGF8-silenced ovarian cancer cells." (PMID 39309198, 2024). "Conclusively, FGF8 and associated hub genes help in the progression of ovarian cancer, and their overexpression may lead to higher immune infiltration, poor prognosis, and poor survival." (PMID 39309198, 2024). "Therefore, this study was designed to gain more functional insights into FGF8 expression and understand the FGF8-linked pathways and mechanisms associated with the pathogenesis of ovarian cancer." (PMID 39309198, 2024). "In FGF8-silenced ovarian cancer cells, the downregulation of several proteins directly linked to the growth of cancer implies that FGF8 plays a significant role in the development of ovarian cancer." (PMID 39309198, 2024). "Targeting FGF8 may be an effective treatment strategy for some cancer types, including ovarian cancer, as various studies have linked abnormal FGF8 expression to the onset and progression of different cancers." (PMID 39309198, 2024). "Therefore, the relationship between the expression of hub genes of the FGF8 protein network and immune cell marker genes suggests that FGF8 is implicated in modulating tumor immunology in ovarian cancer." (PMID 39309198, 2024). "Upon correlating our study's findings with the existing literature, we observed that silencing FGF8 in ovarian cancer cells resulted in the downregulation of several proteins associated with cancer progression, including SLC7A5, FHL2, SPATS2L, and DAD1." (PMID 39309198, 2024). "Proteins were extracted from FGF8-expressing (control) and FGF8-silenced ovarian cancer cells and processed for differential proteomics analysis by LC-MS/MS." (PMID 39309198, 2024). "LC-MS/MS-based quantitative proteomics analysis identified 418 DEPs, and most of them were downregulated in FGF8-silenced ovarian cancer cells." (PMID 39309198, 2024). "Out of 418 DEPs identified in the FGF8-silenced ovarian cancer cells, 414 proteins were downregulated, and only four proteins were upregulated." (PMID 39309198, 2024). "In the FGF8-silenced ovarian cancer cells, differential proteomics found downregulated expression of many proteins connected to the cancer growth, indicating the significant involvement of FGF8 in the development and spread of ovarian cancer." (PMID 39309198, 2024). "We employed ELISA and IHC to examine the expression of FGF8 in the saliva and tissue samples of epithelial ovarian cancer (EOC) patients and controls." (PMID 37762545, 2023). "Based on these observations, it can be concluded that FGF8 promotes ovarian cancer progression and metastasis by facilitating ECM and cell adhesion signaling." (PMID 37762545, 2023). "The mounting data suggest that FGF8 promotes carcinogenesis, progression, and metastasis in various cancers including ovarian cancer." (PMID 37762545, 2023). "A reduced expression of such proteins in FGF8 knockdown cells strengthens the hypothesis that FGF8 is involved in the growth of ovarian cancer and that all these proteins function as an interconnected network." (PMID 39309198, 2024). "In this study, high-throughput quantitative and differential proteomics analysis was carried out in FGF8-silenced cells to delve deeper into the functions of FGF8 and related molecular interactions and pathways, contributing to the progression of ovarian cancer." (PMID 39309198, 2024). "Recently, we observed that FGF8 silencing reduces the cancer-promoting properties of ovarian cancer cells, and thus, this study aimed to understand how FGF8 regulates the development of ovarian cancer." (PMID 39309198, 2024).
ovarian carcinoma (continued). "Thus, the molecular interplay revealed by FGF8 silencing suggests a significant role for FGF8 in the development and progression of ovarian cancer." (PMID 39309198, 2024). "Furthermore, a migration assay was performed to better understand the correlation between the expression of FGF8 and the ability of ovarian cancer cells to migrate toward a chemoattractant." (PMID 37762545, 2023). "Furthermore, various cell assays were conducted to determine how FGF8 silencing influences ovarian cancer cell survival, adhesion, migration, and invasion to learn more about the functions of FGF8." (PMID 37762545, 2023). "Thus, FGF8 might serve as a possible therapeutic target for ovarian cancer, according to the findings of this study." (PMID 39309198, 2024). "FGF8 silencing showed a substantial growth inhibition effect against SKOV3 cells, highlighting that FGF8 facilitates ovarian cancer cells’ ability to survive for a longer period." (PMID 37762545, 2023). "However, FGF8 expression alterations and its role in ovarian cancer remain unknown." (PMID 37762545, 2023). "Fibroblast growth factor 8 (FGF8) is a growth factor that activates the FGFR receptors and has roles in breast, prostate, and ovarian cancers." (PMID 35158795, 2022). "Fibroblast growth factor 8 (FGF8) aids in the development and metastasis of ovarian cancer; however, its definite role is not clear." (PMID 37762545, 2023). "The effect of FGF8 silencing on the ability of ovarian cancer cells to adhere to the extracellular matrix (ECM) was investigated by adhesion assay, and it was observed that the adhesiveness of FGF8-silenced cells reduced by approximately 45% (p-value = 0.0001)." (PMID 37762545, 2023). "Thus, we investigated cell migration and invasion in FGF8-silenced SKOV3 cells and observed a significant reduction in these two cell properties, suggesting that FGF8 also helps ovarian cancer cells in migration and invasion." (PMID 37762545, 2023). "However, no conclusive studies have highlighted a direct role of FGF8 in the progression of ovarian cancer." (PMID 37762545, 2023).
Parkinson disease (5 papers, 2007 to 2025). A progressive degenerative disorder of the central nervous system characterized by loss of dopamine producing neurons in the substantia nigra and the presence of Lewy bodies in the substantia nigra and locus coeruleus. "The in vitro generation of dopaminergic neurons, the type of cells lost in Parkinson's disease patients' brains, requires the inductive molecules sonic hedgehog and FGF8, or an unknown stromal cell derived inducing activity (SDIA)." (PMID 17640353, 2007). "This is the first research in which FSH priming during CEPs of the NS assay is combined with directed differentiation of NSPCs towards the DA pathway by using a defined medium containing SHH, FGF8, and BDNF, a procedure with possible eventual clinical implications for Parkinson’s disease therapy." (PMID 40722636, 2025).
breast tumors (4 papers, 2002 to 2017). "FGF8 is able to function as an oncogene, causing transformation of NIH3T3 cells and inducing breast tumours in transgenic mice expressing FGF8 under an MMTV promoter." (PMID 11953856, 2002). "It has been known for many years that FGF8 and FGF10, both ligands for FGFR2, are overexpressed in human breast tumors, suggesting that antibodies to screen for active FGFR2 would be very useful." (PMID 23343422, 2013). "The results also suggest that the expression of FGFR1 itself is regulated by FGF-8 and FGF signaling, which may be of importance in breast tumors expressing FGFs at a high level." (PMID 23185502, 2012).
cleft palate (4 papers, 2015 to 2023). Cleft palate is a fissure type embryopathy that affects the soft and hard palate to varying degrees. "Fgf8 overexpression in mice results in cleft palate, while Fgf10, a loss of which also results in cleft palate, seems to function in cooperation with Wnt signaling." (PMID 30760477, 2019).
orofacial cleft (4 papers, 2015 to 2025). A disorder of facial skeleton that is characterized by cleft lip and/or cleft palate that result in feeding, speech and hearing problems caused by failures during development. "Although it is unknown whether the current missense mutation in FGF8 leads to functional loss or activation, it suggests that rare coding variants in FGF8 might contribute to the genetic architecture of orofacial clefts." (PMID 40575596, 2025). "We therefore investigated whether alterations in Tfap2a could also influence phenotypic variance as a potential mechanism for interactions with Fgf8 gene dosage in modifying orofacial clefting." (PMID 25381013, 2015).
Anxiety (3 papers, 2014 to 2019). Intense feelings of nervousness, tension, or panic often arise in response to interpersonal stresses. "FGF8-deficient mice display increased anxiety-like behavior, while FGF21 administration in rats induces anxiogenic behavior." (PMID 30804785, 2019). "This is consistent with previous studies reporting that stress can precipitate anxiety-like behavior as well our finding that Fgf8 deficiency is associated with increased baseline anxiety-like behavior." (PMID 24992493, 2014). "The goal of this study is to extend our previous findings by examining if Fgf8 deficiency disrupts the activation of DR serotonergic neurons, their functional output to anxiety- and panic-related projection regions, and anxiety-like behavior following stress." (PMID 24992493, 2014). "This anxiogenic phenotype is not related to differences in the magnitude of the neuroendocrine stress response, and likely reflects a functional disruption of central anxiety-related circuits resulting from Fgf8 deficiency." (PMID 24992493, 2014). "Fgf8-deficient mice had greater stress-induced increases in 5-HIAA in anxiety-promoting DR target regions as well as decreased 5-HIAA in a panic-suppressing DR target region." (PMID 24992493, 2014). "Together these data suggest that disruptions in DRD and DRVL/VLPAG neuronal activation may contribute to increased vulnerability to panic- and anxiety-like behaviors in Fgf8-deficient mice." (PMID 24992493, 2014). "Further, they raise the possibility that humans harboring FGF8 loss-of-function mutations may exhibit abnormal anxiety- and stress-related responses." (PMID 24992493, 2014). "Indeed, we found dysregulated responses to stress in both anxiety-promoting and panic-inhibiting circuits of Fgf8-deficient mice, which were associated with increased baseline anxiety-like behavior." (PMID 24992493, 2014). "We found both anxiety-promoting and panic-inhibiting serotonergic neurocircuits were altered in these mice, and these changes were associated with elevated baseline anxiety-like behavior in Fgf8-deficient mice." (PMID 24992493, 2014). "Together these effects promote an anxiety-like phenotype and may be a consequence of abnormalities within serotonergic neurons, serotonergic DR target regions or with afferent input to the DR due to Fgf8 deficiency." (PMID 24992493, 2014). "Recent studies using Fgf8 hypomorphic mice showed that the adult heterozygous (+/neo) Fgf8 hypomorphic mice exhibited higher levels of anxiety than their wild-type (WT) counterparts." (PMID 26537115, 2015). "Together these data highlight the importance of developmental Fgf8 signaling in establishing functional anxiety- and panic-related DR serotonergic neurocircuits." (PMID 24992493, 2014). "In conclusion, this study demonstrates that reduced Fgf8 signaling is correlated with increased anxiety-like behavior and dysregulated serotonergic neuron activation and functional output in response to stress- and anxiogenic stimuli." (PMID 24992493, 2014). "Our results provide strong support for an early role of Fgf8 signaling in programming stress- and anxiety-related serotonergic neurocircuits responsible for proper behavioral response to stress." (PMID 24992493, 2014). "Results showed that Fgf8 hypomorphs exhibited 1) an exaggerated response of DR anxiety-promoting circuits and 2) a blunted response of a DR panic-inhibiting circuit to stress, effects that together were associated with increased baseline anxiety-like behavior." (PMID 24992493, 2014). "Wild-type and heterozygous male mice globally hypomorphic for Fgf8 were exposed to acute restraint stress and then tested for anxiety-like behavior on the elevated plus-maze." (PMID 24992493, 2014). "To investigate the functional integrity of stress-, anxiety-, and panic-related serotonergic circuitries in Fgf8 HET mice, we quantified the percentage of serotonergic cells that co-expressed c-Fos and Tph (c-Fos/Tph-ir) following restraint stress." (PMID 24992493, 2014).
Anxiety (continued). "Additionally, recent studies indicated that adult heterozygous (+/neo) Fgf8 hypomorphic mice exhibit more anxiety-like behaviors than wildtype (WT) mice." (PMID 26537115, 2015). "Indeed, Fgf8+/neo hypomorphic mice exhibited higher levels of anxiety-like behavior, which coincided with a reduction in the number of Tph-expressing neurons in the dorsal raphe nucleus." (PMID 26537115, 2015). "In this study, we used acute restraint stress followed by behavioral testing to examine whether Fgf8 signaling during development is important for establishing functional stress- and anxiety-related DR neurocircuits in adulthood." (PMID 24992493, 2014). "Additional studies are needed to explore these possibilities and whether Fgf8-related structural abnormalities in other brain regions contribute to vulnerability to stress- and anxiety-related behaviors." (PMID 24992493, 2014). "Specifically, these data suggest that Fgf8 signaling is not only critical for the early formation and positioning of DR neurons but also the integration of serotonergic neurons into functional stress- and anxiety-related circuitries." (PMID 24992493, 2014). "Importantly, we recently showed that Fgf8 deficiency is associated with a loss of specific DR serotonergic neurons in the mid- to caudal DRV, DRVL/VLPAG, and DRI subregions and increased anxiety-like behavior." (PMID 24992493, 2014). "Exposure of WT mice to restraint stress increased anxiety-like behavior as measured by the EPM immediately following stress, whereas anxiety-like behavior was equally elevated in both the non-stress and stress Fgf8-deficient mice." (PMID 24992493, 2014). "Increased activation of the DRD in non-stress Fgf8-deficient mice compared to WT non-stress mice is consistent with their anxiety-like phenotype." (PMID 24992493, 2014). "In addition, FGF8 and FGF21 can also affect anxiety behavior, and they exert their influence in opposite directions." (PMID 30804785, 2019). "Second, Fgf8 hypomorphy may, in part, be an explanation for affective disorders involving hyperactivity of the HPA axis, such as anxiety and MDD." (PMID 26537115, 2015). "Second, Fgf8 hypomorphy may, in part, be an explanation for affective disorders involving hyperactivity of the HPA axis, such as anxiety." (PMID 26537115, 2015). "In the anxiety-promoting DR projection sites (BLA, PrL, IL), post hoc analysis revealed stress increased 5-HIAA content in Fgf8 HET mice but not WT mice (p = 0.017, p = 0.010, and p = 0.001, respectively)." (PMID 24992493, 2014).
ciliopathies (3 papers, 2021 to 2025). "Although Fgf signaling is required for UB branching, aberrant FGF8 expression is common in ciliopathies and has been implicated in the craniofacial defects seen in Fuzzy−/− embryos." (PMID 35076510, 2021). "In humans, increased FGF8 signaling is associated with corpus callosum abnormalities in KIF7-related ACLS, another ciliopathy." (PMID 40575596, 2025). "Furthermore, there was a significant downregulation of FGF8, a critical factor for nephron development, further linking aberrant Shh signaling to the ciliopathy observed in our model." (PMID 41141533, 2025). "Interestingly, in nonrenal ciliopathy models, upregulation of FGF8 has been linked to craniofacial abnormalities, further highlighting a crucial connection between defective cilia function and dysregulated FGF signaling." (PMID 41141533, 2025).
craniofacial microsomia (3 papers, 2013 to 2025). "The specific inactivation of FGF8 signaling in PA1 ectoderm in Fgf8;Nes-cre mice leads to first arch syndromes, similar to mandibulofacial dysostosis." (PMID 40575596, 2025). "Interestingly, as Fgf8 dosage decreased in these mouse mutants, we observed facial asymmetry similar to that reported in human syngnathia, hemifacial microsomia, and in a high proportion of craniofacial malformations and syndromes." (PMID 24385915, 2013).
craniosynostosis (3 papers, 2015 to 2020). Craniosynostosis is defined as the premature fusion of one or more cranial sutures leading to secondary distortion of skull shape resulting in skull deformities with a variable presentation. "Whereas moderate Fgf8 overexpression resulted in delayed ossification followed by craniosynostosis of the coronal suture, higher Fgf8 levels promoted a loss of ossification and favored cartilage over bone formation across the skull." (PMID 29752281, 2018). "Insufficient FGF8 in developing skull bone results in craniosynostosis, and excess FGF8 severely disrupts intramembranous craniofacial ossification." (PMID 32916911, 2020). "First, the cranial vault has a dose-dependent response to FGF8 signaling, with moderate levels of Fgf8b overexpression leading to coronal craniosynostosis and high levels of Fgf8b overexpression leading to ectopic cartilage formation." (PMID 29752281, 2018). "The role of FGF-8 in CA development was further supported by the observation of prevalent CA among patients with craniosynostosis syndromes as a result of the elevated level of FGF-8 expression." (PMID 26106591, 2015). "Moderate overexpression of Fgf8 in the cranial ectoderm of MR26F8 mice affects this balance, resulting in coronal craniosynostosis and narrowing of the lambdoid suture." (PMID 29752281, 2018).
cryptorchidism (3 papers, 2020 to 2025). The failure of one or both testes of a male fetus to descend from the abdomen into the scrotum during the late part of pregnancy. "Zeidler and coworkers identified two FGF8 heterozygous missense variants (p.Gly29_Arg34dup, p.Pro26Leu) in two different patients by conducting a targeted FGF8 sequencing on 78 VATER/VACTERL and VATER/VACTERL-like individuals, and both patients presented with bilateral cryptorchidism." (PMID 40575596, 2025).
gastric cancer (3 papers, 2020 to 2025). A primary or metastatic malignant neoplasm involving the stomach. "However, the high expression of FGF8 predicts a good prognosis in our results, which is contrary to the results for gastric cancer, and further research is needed to clarify its role." (PMID 34526059, 2021). "In tumors, high expression of FGF8 affects EMT through the BRG1/Snai1/E-cadherin pathway and promotes tumor proliferation and invasion of gastric cancer." (PMID 34526059, 2021). "Five gastric cancer cell lines, MNK7, MNK45, MNK74, NUGC3, and NIGC4, were examined FGF8 expression at protein and mRNA levels." (PMID 32071290, 2020). "In the training cohort, a prognostic model for gastric cancer was developed using univariate and multivariate Cox regression analyses, along with stepwise regression, incorporating the genes SNCG, MNAT3, DDO, ITGAD, FGF8, and ABCB5." (PMID 41323282, 2025).
Infertility (3 papers, 2015 to 2022). "Second, an interesting paradox is that while a fraction of humans with Fgf8 haploinsufficiency experiences absent puberty and infertility, Fgf8 Het mice consistently go through puberty and propagate offspring." (PMID 26441841, 2015).